NFYC-AS1 (NFYC antisense RNA 1)
Synonyms: 0808y08y
Gene: Long non-coding RNA gene on chromosome 1 (40,669,089 to 40,692,086, reverse strand). Ensembl gene ENSG00000272145.
Diseases named in the same sentence as NFYC-AS1 in open-access papers:
NFYC-AS1 is named in the same sentence as 5 diseases in open-access papers, as found by Europe PMC text mining. Sharing a sentence is not in itself a finding about the gene and the disease. The quoted sentences say what the papers report.
lung adenocarcinoma (1 paper, 2023). A carcinoma that arises from the lung and is characterized by the presence of malignant glandular epithelial cells. "Recently, NFYC-AS1 (Nuclear transcription factor Y subunit C antisense RNA 1) has also been shown to promote lung adenocarcinoma development through autophagy, apoptosis, and the oncogenic proteins MET/c-Myc38." (PMID 37821547, 2023).
lung carcinoma (1 paper, 2024). "From a therapeutic perspective, NFYC-AS1 knockdown simultaneously repressed genes that represent vulnerabilities of all lung cancer histotypes." (PMID 38467619, 2024).
lung squamous cell carcinoma (1 paper, 2024). "Knockdown of NFYC-AS1 by antisense oligonucleotides impairs cell growth in lung squamous cell carcinoma and small cell lung cancer cells, a phenotype recapitulated by CRISPR/Cas9-deletion of its transcription start site." (PMID 38467619, 2024).
cancer (1 paper, 2024). A tumor composed of atypical neoplastic, often pleomorphic cells that invade other tissues. "The cancer-specific NFYC-AS1 upregulation, which can be partly explained by transcriptional activation by NF-Y or E2Fs as a consequence of RB1 mutations, may indeed exacerbate cell proliferation by facilitating mitotic progression." (PMID 38467619, 2024). "We found that NFYC-AS1 depletion by either ASOs or CRISPR/Cas9 results in cell growth impairment in both RB1-wt and -mut cancer cells, mainly due to downregulation of G2/M cell cycle phase genes." (PMID 38467619, 2024).
NFYC-AS1 also shares sentences with these, for which no sentence is quoted: small cell lung carcinoma (1 paper).